COL11A2 (collagen type XI alpha 2 chain)
Diseases named in the same sentence as COL11A2 in open-access papers (continued):
Sharing a sentence is not in itself a finding about the gene and the disease.
melanoma (2 papers, 2021 to 2025). A malignant, usually aggressive tumor composed of atypical, neoplastic melanocytes. "It offers a framework for subtype-specific treatment strategies, and identifies COL11A2 as a potential target in immune-cold melanomas." (PMID 40574832, 2025). "Transcriptomic analysis indicated increased COL11A2 expression in melanoma tissues relative to adjacent normal tissues, implying its role in tumorigenesis." (PMID 40574832, 2025). "In melanoma cells, COL11A2 silencing significantly reduced proliferation, migration, and invasion, induced apoptosis, and partially reversed EMT phenotypes." (PMID 40574832, 2025). "Functional characterization of subtype-specific genes such as COL11A2 further supports their potential as therapeutic targets and paves the way toward personalized treatment paradigms in melanoma." (PMID 40574832, 2025). "We examined COL11A2 expression in multiple melanoma cell lines, selecting A-375 and SK-MEL-31 due to their higher expression levels." (PMID 40574832, 2025). "Western blot analysis demonstrated increased levels of pro-apoptotic cleaved caspase-3 (c-caspase-3) and epithelial marker E-cadherin, alongside decreased levels of anti-apoptotic Bcl-2 and mesenchymal marker Vimentin, reinforcing the oncogenic function of COL11A2 in melanoma." (PMID 40574832, 2025). "Given the structural and functional similarities within this collagen subfamily, COL11A2 may function analogously to promote melanoma progression by reinforcing a fibroblast-rich, immunosuppressive microenvironment." (PMID 40574832, 2025). "To validate the functional significance of COL11A2, a key gene in the Prognostic Index Score (PIS) model, we investigated its expression in melanoma." (PMID 40574832, 2025). "Among the top genes with differentially spliced isoforms between primary melanomas and benign melanocytic nevi were RAB6B, MSR1, LYPD1, and COL11A2." (PMID 34281234, 2021).
Stickler syndrome type 3 (2 papers, 2013 to 2022). "In type 3 Stickler syndrome (STL3, COL11A2), no ocular symptoms are observed as Col11a2 is not expressed in the eyes." (PMID 36140739, 2022).
tendinopathy (2 papers, 2016 to 2022). "In conclusion, four strong candidate genes (COL11A2; ELN; ITGB3; LOX) were identified as differentially expressed in tendinopathy, functionally linked to features of tendinopathy and implicated in the aetiology of other connective tissue diseases." (PMID 26804977, 2016). "The current study identified four strong candidate genes (COL11A2; ELN; ITGB3; LOX) that are differentially expressed in tendinopathy, functionally linked to features of tendinopathy and previously implicated in the aetiology of other connective tissue diseases." (PMID 26804977, 2016).
chondrodysplasia (1 paper, 2013). "The chondrodysplasia has a more severe phenotype with secondary joint problems and the COL11A2 gene has already previously been excluded to be causative for this phenotype." (PMID 23527306, 2013).
chondrosarcoma (1 paper, 2013). A malignant cartilaginous matrix-producing mesenchymal neoplasm arising from the bone and soft tissue. "The COL11A2-reporter vector directed substantial GFP expression in human chondrosarcoma (HCS-2/8) cells but not in HDFs." (PMID 24146984, 2013).
Cirrhosis (1 paper, 2015). A chronic disorder of the liver in which liver tissue becomes scarred and is partially replaced by regenerative nodules and fibrotic tissue resulting in loss of liver function. "Patients with cirrhosis showed increased expression in blood of eight genes coding for collagen synthesis COL4A6, COL5A1, COL11A2, COL12A1, COL27A1, COL28A1, COL23A1, COL14A1." (PMID 26317806, 2015).
dwarfism (1 paper, 2013). "Using a positional candidate gene approach, we have identified the c.143G>C variant in the canine COL11A2 gene as the most likely causative variant for an inherited mild disproportionate dwarfism in Labrador Retrievers, which we term skeletal dysplasia 2 (SD2)." (PMID 23527306, 2013).
Exotropia (1 paper, 2022). A form of strabismus with one or both eyes deviated outward. "In summary, we present three separate cases of WS with congenital exotropia and find four novel variants in PAX3, COL11A2 and SOX10 genes." (PMID 36118891, 2022).
goiter (1 paper, 2024). Enlargement of the thyroid gland usually caused by lack of iodine in the diet, hyperthyroidism, or thyroid nodules. "The qPCR results demonstrated that Col11a2 was significantly upregulated in the 10-week and 20-week thyroid goiter mice, suggesting its association with goiter." (PMID 39558975, 2024). "The integral optical density values (IOD) of Col11a2 immunohistochemistry in the goiter tissues were significantly higher than that in the control group (Figure 3D1)." (PMID 39558975, 2024). "Compared to that in the 20-week control group, Col11a2 protein expression in the 20-week goiter tissues was significantly increased." (PMID 39558975, 2024). "The qRT−PCR results showed that the Col11a2 mRNA was significantly increased both in the 10-week and 20-week goiter tissues." (PMID 39558975, 2024). "Increased Col11a2 expression was also identified by qRT−PCR and Western blot in the mice goiter tissues." (PMID 39558975, 2024). "IHC results showed that compared to the control group, Col11a2 in the 10-week and 20-week goiter tissues displayed significant brown staining (Figures 3D2-5), and the brown staining in the 20-week goiter tissues was more pronounced than that in the 10-week group." (PMID 39558975, 2024). "Therefore, Col11a2 involved goiter progress may be related to fibrosis and iodine regulation." (PMID 39558975, 2024). "WB results showed that compared to that in the 10-week control group, Col11a2 protein expression in the 10-week goiter tissues of mice was increased, but the difference was not statistically significant." (PMID 39558975, 2024).
Hip dysplasia (1 paper, 2026). The presence of developmental dysplasia of the hip. "We identified three genome-wide significant novel loci, COL11A2, CALN1 and TRPM7, associated with hip dysplasia without dislocation." (PMID 41912496, 2026).
Insulin resistance (1 paper, 2021). Increased resistance towards insulin, that is, diminished effectiveness of insulin in reducing blood glucose levels. "Likewise, COL11A2 exhibited higher methylation levels in the VAT of individuals with insulin resistance compared to normal insulin sensitivity controls." (PMID 33803198, 2021).
iridocyclitis (1 paper, 2024). "Lastly, 3 plasma proteins share the same genetic variant with chronic iridocyclitis: AIF1 (coloc.abf-PPH4 = 1.000), AGER (coloc.abf-PPH4 = 0.887), and COL11A2 (coloc.abf-PPH4 = 0.872)." (PMID 38475831, 2024).
ischemic cardiomyopathy (1 paper, 2021). Ischemic cardiomyopathy is a cardiomyopathy in which a weakness in the muscle of the heart due to inadequate oxygen delivery to the myocardium with coronary artery disease being the most common cause. "Upregulation of type XIA2 collagen (COL11A2) in XH corroborates the results of the earlier RNA sequencing study on patients with ischemic cardiomyopathy after allotransplantation." (PMID 33451076, 2021).
Kawasaki disease (1 paper, 2022). A rare inflammatory disease characterized by an acute febrile, systemic, self-limiting, medium-vessel vasculitis primarily affecting children. "In addition, variants in the COL11A2 gene have been reported to be associated with inflammatory disorders including Kawasaki disease, suggesting that abnormalities in type XI collagen may cause deregulation of the immune system." (PMID 35363175, 2022).
liver cancer (1 paper, 2021). An epithelial or non-epithelial malignant neoplasm that arises from the liver. "Interestingly, we found that most of these key node genes play important roles in tumorigenesis (RET, CEACAM5), immune regulation (CTSG, CD79A) and the EMT pathway (COL10A1, COL11A2), suggesting their significant role in the recurrence of liver cancer." (PMID 34956309, 2021).
nodular goiter (1 paper, 2024). Goiter characterized by discrete tissue mass(es) that may or may not produce thyroid hormones. "Furthermore, LNC60 and Col11a2 mRNA levels were found increased in peripheral blood of nodular goiter patients from high water iodine areas of China and have high diagnostic values for nodular goiter while AUC of LNC60 and Col11a2 are 89.97% and 84.85%, respectively." (PMID 39558975, 2024). "We also found a significant increase in Col11a2 expression in patients with nodular goiter." (PMID 39558975, 2024).
orofacial cleft (1 paper, 2017). A disorder of facial skeleton that is characterized by cleft lip and/or cleft palate that result in feeding, speech and hearing problems caused by failures during development. "Several regions mapped to genes that have previously been implicated in the development of orofacial clefts (for example, TBX1, COL11A2, HOXA2, PDGFRA), and over 250 associations were novel." (PMID 28603561, 2017).
osteosarcoma (1 paper, 2023). A usually aggressive malignant bone-forming mesenchymal neoplasm, predominantly affecting adolescents and young adults. "Lastly, COL11A2 overexpression is frequently associated with poor overall and event-free survival in patients diagnosed with osteosarcoma." (PMID 36673024, 2023).
rectal cancer (1 paper, 2025). A primary or metastatic malignant neoplasm that affects the rectum. "There is a co-expression phenomenon between heat stress factor 4 and a series of genes such as COL11A2 in the occurrence and development of colon or rectal cancer." (PMID 40565262, 2025).
Sleep apnea (1 paper, 2025). An intermittent cessation of airflow at the mouth and nose during sleep is known as sleep apnea. "Furthermore, the craniofacial and bone related genes had high posterior probability for associating only for sleep apnea (BMP5, PP = 0.99; COL11A2, PP = 0.98)." (PMID 41332830, 2025).
tumor (8 papers, 2009 to 2025). "We found that the expression levels of seven integrin ligands (COL4A6, COL13A1, FGB, COL19A1, COL18A1, COL14A1, and COL11A2) were negatively correlated with the Gleason score, suggesting that the suppression of integrins and/or their ligands is associated with more advanced tumor grade." (PMID 19653896, 2009). "Upregulated genes included cartilage-associated genes (COMP, MATN3, and COL11A2), collagen- and extracellular matrix-associated genes (COL9A2, SFRP2, and SERPINE2), and tumor metastasis- and progression-associated genes (SLC38A3, FST, ITGA11, and DGKI)." (PMID 36192442, 2022). "The fibrillar collagens COL2A1, COL11A1, and COL11A2 show higher expression in the solid tumour region and other fibrillar collagens, COL1A2 and COL3A1, show higher abundance in the brain/tumour interface region." (PMID 38001067, 2023). "Moreover, COL11A2 was identified as a subtype-enriched oncogenic driver predominantly expressed in CS1/CS3, and its silencing impaired tumor cell proliferation, invasion, and epithelial–mesenchymal transition (EMT) features." (PMID 40574832, 2025). "On the other hand, Col4a1, Col4a3, Col4a5, Col5a3, Col11a2, Col14a1, Col15a1, Col16a1, and Col22a1 were found in normal ECM but not in tumor ECM; Col25a1 was found only in tumor ECM but not in normal ECM." (PMID 36547361, 2022).
cancer (6 papers, 2016 to 2025). A tumor composed of atypical neoplastic, often pleomorphic cells that invade other tissues. "COL11A2 has been shown to be associated with cancer predisposition in a study of 41 cancer-discordant monozygotic twin pairs." (PMID 34281234, 2021). "COL11A2 is essential for skeletal morphogenesis, and has been documented to be up-regulated in several cancers." (PMID 41463320, 2025). "Col11A2 is a marker for cancer and inflammatory enteritis in humans." (PMID 35875524, 2022). "The third genome-wide suggestive pan-cancer DMP was located in the COL11A2 gene, which to our knowledge has not been linked to cancer." (PMID 26798410, 2016). "Additionally, three suggestive pan-cancer DMPs (P < 1.0 × 10−5) were identified for probes cg26079695 in COL11A2, cg27094856 in AXL, and cg21046959 in LINC00340." (PMID 26798410, 2016). "In the osteoblasts_Gapd2 subpopulation, pathways such as proteoglycans in cancer (Col1a1, Col1a2, Hcls1, Hif1a, Stat3, Vav1), IL-17 signaling (Mmp13, Mmp3, S100a9, Ccl7, Cebpb), and ECM–receptor interaction (Col11a2, Col1a1, Ibsp, and Tnn) were activated (p < 0.05)." (PMID 41459160, 2025). "However, studies on the roles of COL11A2 in the progression of cancer are lacking." (PMID 39518157, 2024).
skeletal dysplasia (5 papers, 2013 to 2023). Any Mendelian diseases that affects growth and development of the skeleton. "Mutations of COL11A2 can also cause an skeletal dysplasia called fibrochondrogenesis (OMIM#614524)." (PMID 32396528, 2020). "The COL11A2 gene represents a good functional candidate gene for a skeletal dysplasia phenotype." (PMID 23527306, 2013). "Our results with the new dog variant indicate that the phenotypic spectrum of COL11A2 variants may also include a very mild skeletal dysplasia without any severe hearing impairment." (PMID 23527306, 2013).
autosomal dominant disease (1 paper, 2021). Autosomal dominant form of disease. "Heterozygous mutations in COL11A1 (OMIM 120280) or COL11A2 (OMIM 120290) have been associated with autosomal dominant disease, although COL11A2‐related disease lacks ophthalmic findings as the gene is not expressed in the vitreous." (PMID 33951325, 2021).
endocrine disorders (1 paper, 2023). "The identification of common pathogenic mechanisms in monogenic and endocrine disorders associated with OPLL/DISH, and the development of targeting therapeutics for other relevant pathways such as ACVR1, COL11A2, COL6A, BMP2,4,9, and TGF-β1 are remaining important questions to be addressed." (PMID 37530996, 2023).
COL11A2 also shares sentences with these, for which no sentence is quoted: Hearing impairment (4 papers); connective tissue disorder (3); lumbar disc herniation (3); Micrognathia (2); Stickler syndrome type 2 (2); Anxiety (1); auditory neuropathy (1); Autoimmunity (1); carpal tunnel syndrome (1); CHARGE syndrome (1); chordoma (1); coeliac disease (1); congenital cataracts (1); depression (1); developmental dysplasia of the hip (1); DOORS syndrome (1); dysplasia (1); endolymphatic hydrops (1); fibrochondrogenesis 2 (1); Global developmental delay (1); graft versus host disease (1); hearing disorder (1); heart failure (1); hyperthyroidism thyrotoxicosis (1); Intellectual disability (1); malignant neoplasm of the thyroid gland (1); Marshall syndrome (1); neurodevelopmental disorder (1); neuronal ceroid lipofuscinosis 4 A (1); nonsyndromic hearing loss (1).
A further 16 diseases each share a sentence with COL11A2 in 1 paper.